DDR1 (discoidin domain receptor tyrosine kinase 1)
Diseases named in the same sentence as DDR1 in open-access papers (continued):
Sharing a sentence is not in itself a finding about the gene and the disease.
tumor (continued). "For instance, the proteolytic degradation of collagen I by MT1-MMP, which increases with aging, was shown to decrease DDR1 activation, tumor growth, and inhibition of apoptosis." (PMID 33917302, 2021). "The combination of DDR1 inhibitors and classical chemotherapeutic drugs has been reported to reduce the tumor burden in both orthotopic xenografts and autochthonous pancreatic cancer models." (PMID 33888679, 2021). "The first demonstration of DDR1 involvement in tumor colonization was elegantly established by the Giancotti group." (PMID 33917302, 2021). "In conclusion, the findings presented in this study demonstrated that miR-199b-5p was significantly downregulated in metastatic PCa and exerts tumour-suppressive functions via directly targeting DDR1." (PMID 33239676, 2021). "Here we report a potentially novel mechanism by which a collagen receptor, DDR1, on PDAC cells interacts with type I collagen to attract tumor-associated neutrophils, induce NET formation, and facilitate cancer cell invasion and metastasis." (PMID 34237033, 2021). "This is consistent with our findings that CXCL5, a CXCR2 ligand, is expressed by tumor cells in a DDR1-dependent manner and drives neutrophil activation and NET formation." (PMID 34237033, 2021). "Moreover, DDR1 positive expression was significantly correlated with the high Gleason score (P < 0.001), advanced pathological tumour stage (P = 0.024) and distal metastases (P < 0.001), suggesting a positive association between DDR1 expression and tumour malignant behaviour." (PMID 33239676, 2021). "In Hodgkin’s lymphoma, latent membrane protein 1 (LMP1) induces DDR1 expression in germinal center B cells and protects tumor cells from death." (PMID 33917302, 2021). "Reexpression of DDR1 (MDA-PATC 148KD#32-ex-DDR1) rescued CXCL5 levels in the tumor and plasma as well as CD11b+Ly6G+ TAN infiltration." (PMID 34237033, 2021). "Several kinase-dependent and kinase-independent mechanisms by which DDR1 promotes metastatic progression have been reported, depending on the tumor type and/or the stage of metastasis development." (PMID 32117772, 2020). "In contrast, silencing of DDR1 reduced very early tumor cell adhesion by an average 75% compared to adhesion of control cells." (PMID 32090682, 2020). "In this work, we show that chemical inhibition of MMPs strongly reduces A375 tumor cell invasive migration and that blockage of DDR1 expression reduces tumor cell synthesis of MMP9, while it also reduces proliferation and migration." (PMID 32090682, 2020). "We analyze the effect of DDR1 inhibition in the expression of key signaling mediators for tumor development and analyze the role of DDR1 in pro-invasive cellular functions in response to collagen type I." (PMID 32090682, 2020). "First, in vitro evidence support DDR1 role in local invasion by primary tumor cells and in the invasive properties of disseminated CRC cells, which is essential for metastasis formation." (PMID 32117772, 2020). "Our data demonstrate for the first time that LRP-1 can induce endocytosis of DDR1 in CRC, thus decreasing the ability of the 3D collagen matrix/DDR1 axis to inhibit tumor cell proliferation." (PMID 32582700, 2020). "Regardless, the emerging picture for DDR1’s role in cancer progression is complex, likely involving tumor-suppressive and/or promotive effects." (PMID 33014862, 2020). "Among these, COL4A5 and COL4A6 were each statistically co-overexpressed with DDR1 in the 40 tumor tissues." (PMID 32244515, 2020). "In contrast, during metastasis development, we supposed that LRP-1 expression is down-regulated after cleavage by sheddases leading to a higher expression of DDR1 at the cell surface and then an increased tumor invasion." (PMID 32582700, 2020).
tumor (continued). "Overexpression of DDR1 has been detected in a variety of tumor types and plays diverse oncogenic roles, including prosurvival cell growth and chemoresistance." (PMID 32244515, 2020). "Several in vivo and in vitro studies pin-points DDR1 as a significant promoter of tumor cell invasion." (PMID 32090682, 2020). "In vitro analysis revealed a role for DDR1 in HSCs expression of genes related to cell migration and secretion of pro-migratory chemotactic factors for LSECs and tumor cells, such as interleukins, CXC chemokines, and MMPs." (PMID 33110221, 2020). "We also studied the role of DDR1 in the expression of MMP9, a key regulator of ECM remodeling implicated in tumor invasion through the collagenous microenvironment and in tumor growth." (PMID 32090682, 2020). "Both approaches demonstrate that DDR1 mediates invasive characteristic such as tumor cell adhesion, proliferation, migration and ECM degradation." (PMID 32090682, 2020). "To investigate how DDR1 signaling participates in a pathologic process were collagen plays an important role, we set an in vitro model of tumor-SCs crosstalk." (PMID 33110221, 2020). "Taken together, these results partially recapitulate the associations of DDR1 and PDPN with ALI detected in OSCC tumor tissues." (PMID 32244515, 2020). "Differential expression analysis using GSEA and Limma of the 40 tumor transcriptomes consistently revealed DDR1, PDPN, and COL4A6 as top upregulated genes in tissues with ALI compared to those without (Table A1, Figure A1)." (PMID 32244515, 2020). "Next we used Western Blot to compare the expression levels of several proteins related to tumor cell invasion between cells with high and reduced DDR1 phosphorylation rates." (PMID 32090682, 2020). "PDAC stroma is rich in fibrillar collagens, which support tumor cell survival and promote tumor progression through discoidin domain receptor 1 and 2 (DDR1 and 2)." (PMID 33178608, 2020). "In this work, we established a direct correlation between DDR1 phosphorylation and tumor cell expression of ICAM1 and VCAM1." (PMID 32090682, 2020). "Next, we compared DDR1 protein expression and phosphorylation between SCs maintained overnight in either C26 cells secretomes (tumor-activated SCs) or basal media." (PMID 33110221, 2020). "As a whole, these data show that tumor cells exposed to secretomes from DDR1 silenced HSCs showed a less aggressive invasive behavior than their counterparts exposed to DDR1-expressing HSCs." (PMID 33110221, 2020). "Further use of antitumor therapies based on DDR1 inhibition requires a more in-depth knowledge of cell-specific DDR1 expression and signaling, the mechanisms that activate its signaling, and its functional implication in tumor growth and dissemination." (PMID 32090682, 2020). "Disrupting DDR1 pathway significantly reduced tumor-bone engagement, lowering cancer cell’s potential to metastasize to the bones, and multiple means of doing so has been discovered." (PMID 33262947, 2020). "To strength the results obtained using chemical inhibition of DDR1 phosphorylation, we silenced DDR1 in each tumor cell lines by transient transfection with siRNA against DDR1 (siDDR1), and assayed cell responses in the presence of exogenous collagen." (PMID 32090682, 2020). "Through the data mining of a microarray dataset composed of matched tumor-normal tissues from forty OSCC patients, we distilled overexpressed genes statistically associated with angiolymphatic invasion, including DDR1, COL4A5, COL4A6 and PDPN." (PMID 32244515, 2020). "Our work demonstrated that collagen type I also induces DDR1 mediated synthesis of MMP9 in tumor cells." (PMID 32090682, 2020). "Collectively, the data indicate that the silencing of hepatic DDR1 impairs the generation of a pro-angiogenic, pro-fibrogenic and proliferative microenvironment provided by the crosstalk between tumor cells and the surrounding SCs." (PMID 33110221, 2020).
tumor (continued). "In this work we utilize two approaches to inhibit DDR1 signaling in those tumor cell lines: chemical inhibition and mRNA silencing." (PMID 32090682, 2020). "In this work, we found that DDR1 mediates proliferation in a collagenous culture setting of the three tested tumor cell lines." (PMID 32090682, 2020). "Concerning the role of type I collagen receptors in tumor progression, Roche's group has elegantly recently shown that DDR1 plays a crucial role in the invasion function of metastatic colon carcinoma." (PMID 32426274, 2020). "In conclusion, hepatic DDR1 promotes C26 liver metastasis and favors the pro-metastatic response of SCs to the tumor." (PMID 33110221, 2020). "The role of DDR1 in the regulation of tumor cell proliferation and apoptosis remains poorly documented and somewhat controversial." (PMID 32582700, 2020). "Of the 100 tumor tissues, 81 showed moderate (48%) to strong (33%) expression of DDR1, scoring as 2+ or 3+." (PMID 31116512, 2019). "Taken together, these results demonstrate that the tumour-promoting effects of collagen are mediated via DDR1." (PMID 31717573, 2019). "In summary, we report for the first time that DDR1 is over-expressed in HNSCCs and is likely to be activated in vivo by collagen produced by tumour cells and CAFs to promote tumorigenesis and chemotherapy resistance." (PMID 31717573, 2019). "DDR1 is found preferentially expressed in highly invasive epithelial tumor cells, whereas DDR2 is expressed in tumor stroma." (PMID 31116512, 2019). "Like many other receptor tyrosine kinases, the dysregulated DDR1 display crucial roles in tumor initiation and progression, such as survival, proliferation, adhesion, migration, metastasis, epithelial-mesenchymal transition (EMT) and drug resistance." (PMID 31253192, 2019). "The data showed that DDR1 exhibited higher expression in most OSCC patients (82.5%) in the tumour tissues than the matched normal tissues." (PMID 31253192, 2019). "Having demonstrated collagen expression in both tumour cells and CAFs, we next examined the expression of DDR1, a collagen-activated tyrosine kinase receptor." (PMID 31717573, 2019). "In addition, of five DDR1 isoforms, two are kinase‐deficient receptors for missing lacking kinase domain or kinase inactive, which may contribute to the inefficient tumor suppression ability of small molecular inhibitors targeting kinase domain of DDR1." (PMID 31116512, 2019). "Earlier work has shown that collagens have a pro-survival and anti-apoptotic function in virus-transformed tumor cells by binding to their receptor DDR1, which results in JNK-, ERK- and p38 MAPK-signaling." (PMID 31708905, 2019). "Overexpression of DDR1 in non‐small lung cancer cells and hepatocellular carcinoma significantly promotes tumor cell motility." (PMID 31116512, 2019). "Knockdown of DDR1 in HNSCC cells demonstrated that these tumour-promoting effects of collagen are mediated by DDR1." (PMID 31717573, 2019). "And this result has also been confirmed by another tissue array cohort which indicate that DDR1 were highly expressed in OSCC specimens, and their overexpression levels were associated with tumor grades (p < 0.05)." (PMID 31253192, 2019). "The clinical relevance of this DDR1 activity is supported by the strong increase in DDR1 phosphorylation in metastatic CRC lesions compared with matched primary tumours and healthy tissues." (PMID 29438985, 2018). "By phosphoproteomic analysis, we then identified BCR as an important DDR1 substrate involved in the maintenance of the β‐catenin oncogenic signalling necessary for tumour cell invasion." (PMID 29438985, 2018). "The results showed that there was an obvious positive correlation between TM4SF1 and DDR1 mRNA expression in tumor tissue samples." (PMID 28368050, 2017).
tumor (continued). "In our study, low concentrations of 7rh benzamide (0.18 or 0.54 μM) suppressed the activation of DDR1 and tumor cell activity by collagen in vitro." (PMID 28143619, 2017). "Luciferase reporter assay also confirmed that, as a receptor tyrosine kinase, DDR1 was strictly regulated by the tumor suppressor miRNA, miR-199a-3p." (PMID 28743276, 2017). "To date, DDR1 has been shown to play an important role in cancer progression by regulating the interactions of tumor cells with the surrounding collagen matrix, therefore leading to pro-migratory and pro-invasive responses." (PMID 27384677, 2016). "Upregulation of transforming growth factor beta 1 (TGFβ1), following DDR1 silencing, is thought to induce tumor cell growth arrest." (PMID 27014069, 2016). "Among these receptors, DDR1 has been found to be highly expressed in invasive tumors indicating its critical role as a regulator of cell invasion and subsequent tumor metastasis." (PMID 27014069, 2016). "The precise molecular mechanisms through which DDR1’s impacts on tumor development and differentiation have yet to be elucidated." (PMID 26297342, 2015). "Consistent with the RT-qPCR results, an increase in DDR1 expression was observed in all of the 4 PDAC tissues compared with the matched adjacent non-tumor tissues." (PMID 26297342, 2015). "Overexpressed mTOR, Met, CHC, and DDR1 were verified in HCC tumor tissues, as compared with precursor and normal liver tissues." (PMID 25861255, 2015). "The DDR1 mRNA levels were significantly increased in 19/30 PDAC tissue samples compared with the matched adjacent non-tumor tissue samples (P = 0.002)." (PMID 26297342, 2015). "The data suggest that reduced expression of DDR1 significantly inhibited BXPC3 tumor cell migration, delaying wound closure." (PMID 25369402, 2014). "We demonstrated that silencing of DDR1 inhibited tumor cell growth and motility, and induced TGFBI expression, both in vitro and in vivo." (PMID 25369402, 2014). "Although exogenous collagen has a modest effect on clonogenic growth and lateral migration of tumor cells, the DDR1 knockdown phenotype remains the same either in the presence or absence of collagen." (PMID 25369402, 2014). "Next, we screened a small panel of tumor cell lines to compare the levels of DDR1 and TGFBI expression by ELISA in order to identify additional models with similar expression profiles as BXPC3." (PMID 25369402, 2014). "Several studies suggested a potential role of DDR1 in tumor cell migration and invasion, usually mediated by extracellular matrix degradation; in addition, also DDR1 mRNA is predicted to be a potential target of miR-199a-5p." (PMID 24839982, 2014). "BXPC3 tumor xenografts demonstrated reduced growth with DDR1 knockdown, and the same xenograft tumors exhibited an increase in TGFBI expression level." (PMID 25369402, 2014). "Overexpression of DDR1 in several tumor cell lines showed an enhanced transformed phenotype with increased anchorage independent growth and tumorigenic potential in nude mice." (PMID 25369402, 2014). "Statistical analysis of tumor size data on day 25 indicated smaller tumors in the DDR1 shRNA5 group than those in the parental (p<0.0001) or NT shRNA group (p<0.01)." (PMID 25369402, 2014). "Here, we show that exogenous addition of recombinant TGFBI to BXPC3 tumor cells inhibited clonogenic growth and migration, thus recapitulating the phenotypic effect observed from DDR1 silencing." (PMID 25369402, 2014). "Tumor growth monitored for 25 days showed that DDR1 knockdown resulted in approximate 50% tumor growth inhibition compared to the control groups." (PMID 25369402, 2014). "Microarray analysis of tumor cells demonstrated upregulation of TGFBI expression upon DDR1 knockdown, which was subsequently confirmed at the protein level." (PMID 25369402, 2014). "From both analyses, we identified TGFBI as one of the genes that was upregulated upon DDR1 knockdown in BXPC3 tumor cells." (PMID 25369402, 2014).
tumor (continued). "Together, these data suggest that DDR1 expression level influences tumor growth in part via modulation of TGFBI expression." (PMID 25369402, 2014). "Taken together, these data suggest that i) miR199a-5p has a role in regulating tumor dissemination induced by hypoxia, and that ii) miR-199a-5p modulates tumor cell migration, at least in part by targeting DDR1." (PMID 24839982, 2014). "In tumor cells and xenografts, DDR1 knockdown was highly significant compared to parental and NT shRNA cells (p<0.0001)." (PMID 25369402, 2014). "We identify critical collagen-binding surface receptors on the tumor cells, including the discoidin domain receptor 1 (DDR1) and E-Cadherin (E-Cad), which interact with COLXV and appear to mediate its function." (PMID 23991074, 2013). "With regard to overall survival, high tumor DDR1 expression showed a tendency toward a poorer outcome, but this trend was not statistically significant (p = 0.064)." (PMID 21541037, 2011). "These proteins, which include CCL5, MAPKs, ERK and DDR1, have been reported to be involved in tumor development." (PMID 22174909, 2011). "In conclusion, identification of the miR-199a-5p:DDR1 target pair and its crucial role in tumor cell invasion highlight the translational relevance for both prognostic prediction and targeted molecular therapy for patients with HCC." (PMID 20799954, 2010). "Mature miR-199a-5p and DDR1 expression were evaluated in tumor and adjacent non-tumor liver tissues from 23 patients with HCC undergoing liver resection and five hepatoma cell lines by the use of real-time quantitative RT-PCR (qRT-PCR) analysis." (PMID 20799954, 2010). "In line with this clinicopathological observation, we found that DDR1 gene silencing by transfection of miR-199a-5p into HepG2 cells significantly decreased tumor cell invasion in vitro." (PMID 20799954, 2010). "Of note, DDR1 appears to be preferentially expressed in tumour cells, whereas DDR2 is expressed in tumour stroma." (PMID 17299390, 2007). "Notably, discoidin domain receptor tyrosine kinase 1 (DDR1) was identified as a functional inhibitor of tumor cell invasion." (PMID 42092764, 2026). "DDR1 inhibits the host’s anti-tumor immunity, and anti-DDR1 antibodies could serve as an alternative anticancer immunotherapy for a variety of cancer types." (PMID 40564099, 2025). "DDR1 acts as a collagen sensor, critical for cell migration, adhesion, and invasion, with its tumorigenic or antitumorigenic effects depending on factors such as tumor stage, type, downstream signaling, and the specific collagen isoform involved." (PMID 40721833, 2025). "The interaction between DDR1 and various collagens suggests that DDR1 may contribute to tumor progression and metastasis by modulating ECM remodeling and dynamics." (PMID 40869052, 2025). "Conditional DDR1 knockout models or co-culture systems could clarify how DDR1 signaling in tumor or stromal cells drives macrophage polarization or modulates cytokine production favoring immunosuppressive T cell subsets." (PMID 40869052, 2025). "Positive scores from CRISPR-based lymphocyte–tumor co-culture screens indicated that DDR1 disruption sensitizes tumor cells to cytotoxic T and NK cells, while adverse (positive) associations with ICB survival were consistently observed in several independent cohorts." (PMID 40869052, 2025). "However, another study reported that pharmacological inhibition or genetic deletion of DDR1 increased tumor burden and inadvertently promoted a protumorigenic microenvironment." (PMID 41394854, 2025). "Depending on the cell type and tumour origin, DDR1 may be a pro‐ or anti‐tumour receptor; this warrants further investigation." (PMID 40105492, 2025). "We next evaluated the in vivo efficacy of NSC632839 against DDR1-positive A549 tumor growth." (PMID 40713963, 2025).